RUNX2 (RUNX family transcription factor 2)
Diseases named in the same sentence as RUNX2 in open-access papers (continued):
Sharing a sentence is not in itself a finding about the gene and the disease.
prostate carcinoma (continued). "RANKL expression is higher in prostatic cancer tissue (indicated by an arrow in A’) adjacent to normal tissue (indicated by an asterisk in A’); b) Diffuse cytoplasmic and intense nuclear distribution of RUNX2 was observed in both normal and prostate cancer tissue sections (C, D, C’ and D’)." (PMID 22966907, 2012). "In prostate cancer, exosomal miR-1275 secreted by cancer cells modulates osteoblast proliferation and activity through targeting the SIRT2/RUNX2 cascade." (PMID 40476182, 2025). "CT/MRI-guided biopsy differentiates osteoblastic/osteolytic prostate cancer metastases, molecular markers (ERG fusion, RUNX2, Wnt dysregulation) indicate osteo-tropic mechanisms correlatable with imaging." (PMID 41458551, 2025). "It has been reported in prostate cancer that integrin αvβ3 and CD44 pathways function in osteoclastogenesis via a RUNX2/Smad5-signaling axis, which provides evidence for RUNX2-related bone destruction in MM." (PMID 36897488, 2023). "Previous studies have shown that RUNX2 contributes to the progression of breast and prostate cancer-related osteolytic bone destructions by inducing TGFβ signaling and the CTGF-RUNX2-RANKL axis." (PMID 36897488, 2023). "In prostate cancer, an intracellular form of CD44—released upon extracellular domain cleavage—is transported into the nucleus, where it can bind to RUNX2 leading to its activation and subsequent increased MMPs expression." (PMID 35538545, 2022). "RUNX2 and MMP-9 are considered as markers of breast and prostate cancer cells, which metastasize to bone." (PMID 31331331, 2019). "Noteworthy, the cancer lesions with higher value of SUV max (BM+ patients) were characterized by the presence of calcium-phosphate calcifications and a higher number (>300) of RUNX2-positive and RANKL-positive prostate cancer cells." (PMID 30627063, 2018). "In order to characterize ongoing bone cell activity in clinical cases of prostate cancer bone metastasis, we selected a set of genes to represent osteoclast activity (ACP5, CTSK, MMP9), osteoblast activity (ALPL, BGLAP, RUNX2) and osteocytes (SOST)." (PMID 29670000, 2018). "Prostate specific antigen and Runt-related transcription factor 2 (RUNX2), a bone-specific transcriptional regulator expressed in metastatic prostate cancer cells, are regulated by ligand activation of GPRC6A." (PMID 28659174, 2017). "CRISPR/Cas9 editing of PC-3 cells showed impaired ligand-stimulated expression of MMP9, VEGF, BMP3, PSA, RUNX2, and OCN, which are involved in prostate cancer progression." (PMID 28659174, 2017). "The TRAMP mouse is ideal to study the dynamic expression of Runx1 and Runx2 in the transition from a normal gland to tumorigenic tissue as TRAMP prostates develop morphologically and histologically similar tumors to human prostate cancer." (PMID 27634876, 2016). "In prostate cancer cells, stable expression of constitutively activated AKT (myr-AKT) induces the expression of RUNX2 mRNA and its target genes, such as PIP, PGC, MMP9 and MMP13." (PMID 26204939, 2015). "As demonstrated in prostate cancer, FOXO4 antagonizes RUNX2 activity by physically interacting with and preventing RUNX2 to induce the expression of pro-metastatic genes, such as PIP and PGC." (PMID 26204939, 2015). "The partnership between RUNX2 and SMADs in promoting EMT and tumor progression is illustrated in human breast and prostate cancer." (PMID 26204939, 2015). "In addition, in prostate cancer, CKAP2, LASP1, BIRC5, WASF1, ASAP1 and RUNX2 mRNAs were recently identified as new miR-203 targets, suggesting that miR-203 could be a new prognostic marker and a therapeutic target in metastasis of prostate cancer." (PMID 23285092, 2012). "Smad 5 interaction was more with RUNX2 and this interaction regulates the expression of RANKL in prostate cancer cells." (PMID 22966907, 2012).
prostate carcinoma (continued). "We show here that phosphorylation of Smad 5 by integrin αvβ3 and RUNX2 by CD44 signaling, respectively, regulates RANKL expression in human-derived PC3 prostate cancer cells isolated from bone metastasis." (PMID 22966907, 2012). "Prostate cancer patients with lymph node and bone metastases display a low PTEN expression and, therefore, a high AKT activation, which is correlated with the overexpression of RUNX2 in the tumor cells." (PMID 34064589, 2021). "However, several studies have shown that factors such as MMP-7, Runx2, and CTGF can alter osteosclerotic bone metastasis to an osteolytic phenotype in prostate cancers." (PMID 33549040, 2021). "Furthermore, CD44 regulates the phosphorylation of RUNX2, which is essential for RANKL expression in prostate cancer cells." (PMID 33062960, 2020). "In a previous study, overexpression of Runx2 in prostate cancer cells revealed extensive non-promoter binding." (PMID 24655370, 2014). "This phenotype is probably the combinatorial effect of Runx2 on BMP-3B suppression and activation of genes related to invasion and migration (e.g., MMPs), as Runx2 is known to promote migration and invasive potential of breast and prostate cancer cells." (PMID 22537242, 2012). "Prostate cancer up-regulation has been previously documented for ATF3, RUNX2 and ERG." (PMID 20021671, 2009). "Additionally, we have identified Runx2, the master transcription factor for osteoblast differentiation as a key regulator of survivin transcription in prostate cancer cells, and observed that BMP signaling is also involved in up-regulation of Runx2 protein expression in these cells." (PMID 23936028, 2013). "Conversely, osteoclast differentiation was prevented by CM from PC3 cells knockdown of RUNX2 (D) suggesting that RUNX2 regulates RANKL expression, and that secretion of RANKL by metastatic prostate cancer cells in the bone microenvironment may support osteoclastogenesis and osteolysis." (PMID 22966907, 2012). "We have shown previously that PC3 prostate cancer cells express GFP and iNOS transgenes as provoked using hOC, but lymph node carcinoma of the prostate (LNCaP) cancer cells do not;19 LNCaP cells are known to express Runx2 to a much lower extent than PC3 cells." (PMID 28325291, 2017).
osteoarthritis (79 papers, 2010 to 2026). A noninflammatory degenerative joint disease occurring chiefly in older persons, characterized by degeneration of the articular cartilage, hypertrophy of bone at the margins and changes in the synovial membrane. "Apart from bone biology, RUNX2 is implicated in osteoarthritis (OA), where its overexpression is linked to OA emergence." (PMID 41511334, 2025). "Runx2 is an important pathogenic factor, while Runx1, Runx3, and Cbfb are protective factors in osteoarthritis development." (PMID 39337587, 2024). "There is a gradual decrease in the mRNA levels of Col2a1, Acan and Sox9 and an increase in Runx2 associated with osteoarthritis." (PMID 39600948, 2024). "Runt-associated transcription factor 2 (RUNX2) is a master transcription factor for chondrocyte hypertrophy that plays an important role in osteoarthritis." (PMID 36915153, 2023). "Several transcription factors have been implicated in the onset and progression of osteoarthritis, including Runx2, C/EBPβ, HIF2α, Sox4, and Sox11." (PMID 32079226, 2020). "Apoptosis is an important factor in osteoarthritis, and Runx2 is a causative molecule of osteoarthritis." (PMID 32244499, 2020). "Conversely, RUNX2, a transcription regulator for type X collagen and established marker for chondrocyte hypertrophy is involved in the calcification and degradation of cartilage matrices and directly implicated in the pathogenesis of osteoarthritis." (PMID 39457070, 2024). "SUPT3H and RUNX2 were found to be associated with osteoarthritis." (PMID 36498562, 2022). "In addition to the oncogenic effects of these proteins, RUNX2 has been shown to be associated with cartilage degradation in patients with osteoarthritis and with osteoclast recruitment in bone remodeling." (PMID 34136397, 2021). "Furthermore, methylation level of the RUNX2 gene has been correlated with the risk for osteoarthritis." (PMID 32079226, 2020). "Similarly, PRP-Exos and PRP-As reversed the decrease in collagen II and RUNX2 protein expression caused by osteoarthritis, promoted cartilage repair and inhibited osteoarthritis." (PMID 31888697, 2019). "Thus, C/EBPβ appears to be implicated in the onset of osteoarthritis in cooperation with Runx2." (PMID 32079226, 2020). "TGF‐β can promote angiogenesis, infiltrate subchondral bone, exacerbate osteoarthritis progression, and increase the expression of terminal differentiation genes such as Mmp13, Runx2, and Col10a1." (PMID 40837199, 2025). "The global knockout of miR-204/211 induces spontaneous osteoarthritis by 15 weeks, while conditional knockout in mesenchymal progenitors displays aging-like phenotypes, and its reduction results in Runx2 accumulation and cartilage degradation." (PMID 41158629, 2025). "A recent study showed that Runx2 overexpression can accelerate the development of post-traumatic osteoarthritis." (PMID 37361231, 2023). "Similar, HIF2a is an upstream regulator of Runx2 which enhances osteoarthritis or accelerates articular chondrocyte differentiation into hypertrophic chondrocytes." (PMID 36815875, 2023). "The results showed that the expression of SFPQ was significantly decreased and the expression of RUNX2 was significantly increased in osteoarthritis cartilage tissue." (PMID 36915153, 2023). "Accordingly, a recent report showed that intra-articular injection of miR-483-5p inhibitor delays the development of osteoarthritis through the reduction in the number of RUNX2-positive chondrocytes." (PMID 36847916, 2023). "The activity of SFPQ and RUNX2 in the bone tissue of patients with osteoarthritis was analyzed using quantitative real-time polymerase chain reaction (qRT-PCR)." (PMID 36915153, 2023). "As a model of osteoarthritis, we recently reported that RUNX2-DNA binding regions were altered by inflammatory conditions." (PMID 36769300, 2023). "Regarding the action of RUNX2 in the adult stage, Runx2 is required for bone metabolism and also plays multiple roles in pathological conditions such as osteoarthritis." (PMID 36769300, 2023).
osteoarthritis (continued). "The deletion of RUNX2 in articular chondrocytes slows the progression of osteoarthritis induced by destabilization of the medial meniscus (DMM) in adult mice." (PMID 36572886, 2022). "WWP2 protects cartilage against osteoarthritis by Runt-related transcription factor 2 (Runx2) poly-ubiquitination and degradation to suppress Adamts5 expression." (PMID 35983977, 2022). "In contrast, the suppression of Runx2 in the articular cartilage will be beneficial for osteoarthritis." (PMID 35628587, 2022). "The upregulation of Runx2 in the articular cartilage will lead to osteoarthritis due to the maturation of chondrocytes and degradation of the cartilage matrix." (PMID 35628587, 2022). "Transcription factor RUNX2 is critical for osteoblast differentiation and chondrocyte maturation and usually upregulated in chondrocytes in osteoarthritis." (PMID 35164658, 2022). "RUNX2 is a primary factor in osteoblast differentiation and has been reported to play an essential role in the development of osteoarthritis." (PMID 35170378, 2022). "To investigate how FA impacted IL‐1β‐induced osteoarthritis chondrocyte degeneration, we examined chondrocyte de‐differentiation markers collagen I and Runx‐2 and chondrogenic genes including collagen II and aggrecan." (PMID 34078001, 2021). "As a result, Runx2 is a vital factor for chondrocyte maturation and participates in the pathogenesis of osteoarthritis." (PMID 34124045, 2021). "The expression of runt-related transcription factor 2 (Runx2), an osteogenic transcriptional activator, is enhanced in osteoarthritis." (PMID 32189997, 2020). "Recently, the progression of osteoarthritis was found to be accelerated in chondrocyte-specific Runx2-overexpressing mice." (PMID 32079226, 2020). "As the transcriptional partner of Runx2 during cartilage development, C/EBPβ is thought to also have a role in the pathogenesis of osteoarthritis." (PMID 32079226, 2020). "The aim of this study was to investigate the role of Notch signaling changes during proliferation and differentiation of chondrocyte, and to testify the mechanism of MMP-13 regulation by Notch and Runx2 expression changes during osteoarthritis." (PMID 31666602, 2019). "In the present study, we found that the accumulation of β-catenin and Wnt5a increased in IL-1β-induced osteoarthritis chondrocytes, and expression of the downstream transcription factor, RUNX2, was also increased." (PMID 31888697, 2019). "A particularly dense number of associations with different bone related phenotypes were present in the RUNX2 5’ region, where variants have been associated to BMD, height, osteoarthritis and ossification of the spine." (PMID 27701424, 2016). "The disruption of RUNX2, as seen in the type II collagen hydrogel, has been shown to block chondrocyte hypertrophy and the progression of osteoarthritis." (PMID 24312400, 2013). "Runx2 modulates chondrocyte hypertrophy and the advancement of osteoarthritis, whereas miR-204 and miR-211 are microRNAs that preserve joint homeostasis by inhibiting osteoarthritis development." (PMID 41158629, 2025). "Moreover, it is known that Runx2 can guide the differentiation of osteoblasts and hypertrophy of chondrocytes, thus contributing to the pathogenesis of osteoarthritis." (PMID 38769993, 2024). "Likewise, in pathological conditions such as osteoarthritis (OA), in which articular chondrocytes develop a hypertrophic phenotype, the upregulation of Runx2 and ALP has been detected, along with Type X collagen, MMP13 and IHH and reduced Type II." (PMID 39791725, 2024). "Similarly, our study showed that RUNX2 is highly expressed in patients with osteoarthritis, as well as mouse primary chondrocytes stimulated by IL-1β also upregulates RUNX2." (PMID 36915153, 2023). "The osteoarthritis therapeutic effect of p-15 requires SFPQ/Akt/RUNX2 signaling." (PMID 36915153, 2023).
osteoarthritis (continued). "Finally, the HDAC4 enzyme, which plays a crucial role during skeletogenesis by inhibiting Runx2, notably as a target of PTHrP, also appears to be involved in the pathogenesis of osteoarthritis with different effects depending on the stage of the pathology." (PMID 36733912, 2023). "Besides its role in chondrocyte differentiation, RUNX2 also seems to play a role in the development of osteoarthritis, as RUNX2-knockout mice are resistant to cartilage degradation." (PMID 37509363, 2023). "Meanwhile, Runx2 conditional knockout mice showed biphasic phenotypes: heterozygous knockout inhibited osteoarthritis and decreased matrix metallopeptidase 13 (Mmp13) expression, while homozygous knockout of Runx2 accelerated osteoarthritis and reduced type II collagen (Col2a1) expression." (PMID 36261443, 2022). "Here, we examined the role of Runx2 and Runx3 for osteoarthritis development in vivo and in vitro." (PMID 36261443, 2022). "Osteoarthritis may be treated by exosomes derived from Runx2-overexpressed bone marrow mesenchymal stem cells (R-BMSCs-Exos)." (PMID 39282499, 2022). "Furthermore, overexpression of RUNX2 in chondrocytes accelerates osteoarthritis progression in adult mice." (PMID 36572886, 2022). "In addition, the expression of Runx2 in osteoarthritis chondrocytes is significantly higher than that of normal chondrocytes." (PMID 34124045, 2021). "Aggrecan, Col-10, MMP-13, SOX6, and Runx2 are closely related to osteoarthritis." (PMID 34926690, 2021). "With the decrease of Runx2, the progression of osteoarthritis is slowed down." (PMID 34124045, 2021). "In contrast to Runx2, Runx1 has been shown to exhibit opposite functions in osteoarthritis." (PMID 32079226, 2020). "Additionally, C/EBPβ can reportedly induce expression of MMP13, a major collagenase for type 2 collagen, in cooperation with Runx2, consequently promoting osteoarthritis." (PMID 32079226, 2020). "Activation of the Wnt/β-catenin signaling pathway could upregulate RUNX2 in osteoarthritis cartilage cells, and downregulation of RUNX2 could alleviate OA." (PMID 31888697, 2019). "In addition, various transcription factors and regulators involved in osteoarthritis progression include RUNX2 (Runt-related transcription factor 2), ADAMTS (a disintegrin and metalloproteinase with thrombospondin motifs), mTOR (mammalian target of rapamycin) and MMPs." (PMID 38235147, 2023). "Several transcription factors, including Runt-related transcription factor 2 (Runx2) and the group C of sex determining region Y-box (SoxC) family members, have been demonstrated to regulate expression of the degradative enzymes of cartilage matrices, which results in the onset of osteoarthritis." (PMID 32079226, 2020). "Runx2 may play an important role in development of osteoarthritis (OA)." (PMID 28539595, 2017). "Among them, RUNX2 and T-Box Transcription Factor 4 (TBX4) are major regulators of chondrogenesis and have previously been identified as effector genes for osteoarthritis." (PMID 40724902, 2025). "P-15 can mitigate chondrocyte damage and osteoarthritis progression by inhibiting cell death and modulating SFPQ-Akt-RUNX2 pathway, offering an opportunity to develop new strategies for the treatment of osteoarthritis." (PMID 36915153, 2023). "MiR-1 can delay the progression of osteoarthritis by inhibiting IHH and IHH regulates RUNX2 through GLI2 to stimulate osteoblast differentiation." (PMID 36766336, 2023). "Nicolai’s study found that the overexpression of SMURF2 reduced the levels of RUNX2 and TGFBR1 in an osteoarthritis system, and our investigation added direct information about the relationship between RUNX2 and TGFBR1." (PMID 36611957, 2022). "Corresponding to the biological reality of cartilage diseases, such as osteoarthritis, OA, in the AC model a switch from the SOX9+ to the RUNX2+ state is possible." (PMID 34869253, 2021).